NEK4 (NIMA related kinase 4)
Description:
Protein kinase that seems to act exclusively upon threonine residues (By similarity). Required for normal entry into proliferative arrest after a limited number of cell divisions, also called replicative senescence. Required for normal cell cycle arrest in response to double-stranded DNA damage.
Synonyms: STK2; NRK2; pp12301
Tractability: Small molecule: a high-quality ligand is known; it belongs to a druggable protein family. PROTAC: it is named in the literature on targeted protein degradation; ubiquitination databases record sites on it; its protein half-life has been measured; a small molecule that binds it is known.
Target class: Other protein kinase NEK family; Kinase; Enzyme; Other protein kinase group; Protein Kinase
Safety:
Unwanted effects reported when the protein is acted on. In parentheses: how it was acted on, where the effect was seen, and who reports it.
neutropenia (source: ClinPGx)
Gene: Protein-coding gene on chromosome 3 (52,708,444 to 52,770,973, reverse strand). Ensembl gene ENSG00000114904.
Subcellular location: Cell projection, cilium; Cytoplasm
Subcellular location (Human Protein Atlas): Cytosol
Gene Ontology:
Molecular function: manganese ion binding; protein serine/threonine kinase activity; ATP binding; protein kinase activity; protein serine kinase activity
Biological process: DNA damage response; mitotic cell cycle; positive regulation of DNA-templated transcription; regulation of cellular senescence; intracellular signal transduction; positive regulation of canonical Wnt signaling pathway; protein phosphorylation; regulation of monoatomic cation transmembrane transport
Cellular component: cytoplasm; cytosol; cilium
Genetic constraint (gnomAD): Loss-of-function variants: 65 observed, 69.03 expected, observed/expected ratio (o/e) 0.94, 90% interval 0.77 to 1.16. The upper end of that interval is the gene's LOEUF score, 1.16, which puts it in group 5 of 6, group 1 being the genes least tolerant of losing a copy. Missense variants: 698 observed, 754.83 expected, observed/expected ratio (o/e) 0.92, 90% interval 0.87 to 0.98. Synonymous variants: 259 observed, 279.35 expected, observed/expected ratio (o/e) 0.93, 90% interval 0.84 to 1.03.
Homologues: Orthologues: chimpanzee NEK4 (99% identical), macaque NEK4 (81% identical), pig NEK4 (78% identical), rabbit NEK4 (78% identical), dog NEK4 (77% identical), mouse Nek4 (72% identical), rat Nek4 (72% identical), zebrafish nek4 (46% identical), tropical clawed frog nek4 (45% identical). Paralogues in human: TNIK (21% identical), MAP4K4 (20% identical), MINK1 (19% identical), SLK (18% identical), STK10 (16% identical), NRK (15% identical), MAP4K3 (14% identical), TAOK2 (14% identical), TAOK1 (14% identical), TAOK3 (13% identical), MAP4K5 (13% identical), MAP4K2 (12% identical), and 23 more.
Diseases named in the same sentence as NEK4 in open-access papers:
NEK4 is named in the same sentence as 41 diseases in open-access papers, as found by Europe PMC text mining. Sharing a sentence is not in itself a finding about the gene and the disease. The quoted sentences say what the papers report.
schizophrenia (10 papers, 2017 to 2025). A major psychotic disorder characterized by abnormalities in the perception or expression of reality. "A study identified that alternative splicing of NEK4 is regulated by sQTLs, which are significantly enriched in schizophrenia-associated loci." (PMID 39734669, 2024). "Many risk genes shared by schizophrenia and BD have been reported to affect dendritic spine morphogenesis, such as NEK4, GNL3, PBRM1, and GLT8D1." (PMID 37443018, 2023). "To further test if rs2535629 conferred schizophrenia risk by modulating the expression of NEK4, GLT8D1, and SFMBT1, we examined the expression level of these three genes in brains of schizophrenia cases and controls using data from the PsychENCODE (559 cases and 936 controls)." (PMID 34978167, 2022). "One was found on chromosome 3p21, where the index schizophrenia-associated SNP (rs2535627, P for schizophrenia association in the PGC GWAS= 4.0 × 10−11) itself was identified as an sQTL SNP significantly associated with an Alt EX of NEK4 (double-corrected P for sQTL=7.8 × 10−5)." (PMID 28240266, 2017). "Closer examination of each schizophrenia-associated loci revealed four regions (each encompasses NEK4, FXR1, SNAP91 or APOPT1), where the index SNP in GWAS is in strong linkage disequilibrium with sQTL SNP(s), suggesting dysregulation of AS as the underlying mechanism of the association signal." (PMID 28240266, 2017). "Furthermore, several GWAS have identified NEK4 as a common risk gene for BD and schizophrenia." (PMID 39950180, 2025). "Interestingly, differential expression analysis of GLT8D1, SFMBT1, and NEK4 suggested that rs2535629 may confer schizophrenia risk by regulating SFMBT1 expression." (PMID 34978167, 2022). "By utilizing the list of sQTL SNPs, we could specify four promising candidate disease susceptibility genes for schizophrenia (that is, NEK4, FXR1, SNAP91 and APOPT1), whose AS are regulated by sQTL SNPs in strong LD with the index SNPs identified in the PGC GWAS." (PMID 28240266, 2017). "This region harbours genes including ITIH4, NEK4, GNL3 and PBRM1 that have previously been linked mechanistically to schizophrenia and related brain changes at cellular and whole brain scales." (PMID 38016951, 2023). "The genomic region of chromosome 3p21.1 contained several genes pleiotropically associated with both SA and schizophrenia, including PBRM1, NEK4, GNL3, ITIH4 and NISCH." (PMID 38016951, 2023). "Recently, a study found that the genetic variants in the 3p21.1 region affect expression of NEK4, GNL3, and PBRM1 in the frontal cortices, which in turn affected dendritic spines, cognitive function, schizophrenia, and bipolar disorder." (PMID 34291596, 2021). "An additional gene, GLT8D1, proximally located to NEK4, also survived correction the schizophrenia and BIP analyses." (PMID 32398653, 2020). "In two of these instances, overexpression was associated with both schizophrenia and BIP: HAPLN4—(schizophrenia: ZTWAS = 5.03, P = 4.66 × 10−7), (BIP: ZTWAS = 5.6506, P = 1.6 × 10−8)], and NEK4—(schizophrenia: ZTWAS = 5.34, P = 9.25 × 10−8), (BIP: ZTWAS = 5.13, P = 2.9 × 10−7)." (PMID 32398653, 2020). "GLN3 (G protein nuclear 3) was similarly significant for schizophrenia and BIP, however, due to its proximity to NEK4 this may arise from the same underlying genomic signal." (PMID 32398653, 2020). "In addition to GLT8D1 and NEK4, our study also suggests that SFMBT1 may be a potential risk gene at this locus, and functional SNP rs2535629 may confer schizophrenia risk by regulating SFMBT1." (PMID 34978167, 2022). "As we have demonstrated the potential role of GLT8D1 in schizophrenia in our previous study and expression analysis showed no significant change of NEK4 and GLT8D1 in schizophrenia cases compared with controls, we focused on SFMBT1 in this study." (PMID 34978167, 2022).
schizophrenia (continued). "Fourth, considering that rs2535629 is associated with the expression of GLT8D1, NEK4, and SFMBT1, we could not rule out the possibility that rs2535629 might confer schizophrenia risk by regulating the expression of GLT8D1 and NEK4." (PMID 34978167, 2022). "NEK4 was conditionally significant in both disorders below the Bonferroni threshold, while in this construct GLT8D1 was only marginally significant for schizophrenia (PConditional = 0.034) and not significant for BIP (PConditional = 0.69)." (PMID 32398653, 2020).
lung carcinoma (8 papers, 2016 to 2025). "NEK4 depletion promoted tumor necrosis factor-related apoptosis-inducing ligand (TRAIL)-induced apoptosis in TRAIL-resistant lung cancer cells and mouse xenograft models through the downregulation of anti-apoptotic protein survivin." (PMID 41001016, 2025). "NEK4 promotes proliferative arrest in fibroblasts and the epithelial-to-mesenchymal transition in lung cancer cells." (PMID 41001016, 2025). "In 2018, along the same lines, Ding and co-workers published that NEK4 is a positive regulator of epithelial-to-mesenchymal transition (EMT) which plays an important role in lung cancer metastasis." (PMID 33435251, 2021). "Park and co-workers reported, for instance, the overexpression of NEK4 in lung cancer and suggested that NEK 4 suppresses Tumor necrosis factor-Related Apoptosis Inducing Ligand (TRAIL)-induced apoptosis, which in turn results into tumor resistance." (PMID 33435251, 2021). "In the study, siRNA library screening in lung cancer cells expressing the E-cadherin promoter-reporter construct revealed that NEK4 is a positive regulator of lung cancer EMT, resulting in increased potential for cells to migrate and invade." (PMID 32294979, 2020). "As inhibition of NEK4 expression downregulated survivin expression, we next investigated survivin and NEK4 expression levels in several lung cancer cells and tissues." (PMID 27602754, 2016). "Increased expression of NEK4 was additionally confirmed in lung cancer tissues of the tissue microarray." (PMID 27602754, 2016). "In lung cancer tissue samples, both NEK4 and survivin expression were highly upregulated in tumors compared to those in adjacent normal tissues in six of eight cases." (PMID 27602754, 2016). "Taken together, these results suggest that inhibition of NEK4 can enhance the anti-tumor activity of TRAIL in lung cancer." (PMID 27602754, 2016). "In the lung cancer context, NEK4 was also demonstrated to regulate the epithelial to mesenchymal transition (EMT), which is a cellular process that occurs in cells that lose their epithelial phenotype and acquire mesenchymal characteristics, and has been linked to cancer cell migration and invasion." (PMID 32294979, 2020). "In addition, expression analysis in cancer tissues showed that NEK4 and survivin were elevated in tumor tissues compared to tumor-adjacent normal tissues (six of eight lung cancer patients and three of five colon cancer patients)." (PMID 27602754, 2016). "Furthermore, expression analysis revealed that both NEK4 and survivin levels were elevated in lung cancer cell lines and patient tissues." (PMID 27602754, 2016). "As with lung cancer tissue, NEK4 expression was also elevated in colorectal tumor tissues, when compared to that in normal tissues (3/5 cases), suggesting that NEK4 is upregulated during tumorigenesis." (PMID 27602754, 2016). "Interestingly, NEK4 was highly upregulated in tumor tissues derived from patients with lung cancer and colon cancer." (PMID 27602754, 2016). "Moreover, it has been reported that NEK4 is frequently overexpressed in lung cancer." (PMID 33435251, 2021). "Thus, this study demonstrates NEK4 as a novel kinase involved in regulation of EMT and suggests that NEK4 may be further explored as a potential therapeutic target for lung cancer metastasis." (PMID 30247800, 2018). "Furthermore, NEK4 was upregulated in lung cancer and colon cancer tissues." (PMID 27602754, 2016). "We found that the Never in Mitosis A (NIMA)‐related kinase‐4 (NEK4) was a positive regulator for lung cancer EMT, resulting in an increased potential for cells to migrate and invade." (PMID 30247800, 2018). "NEK4 may regulate EMT (epithelial–mesenchymal transition) and promote lung cancer metastasis." (PMID 37835513, 2023).
breast carcinoma (5 papers, 2018 to 2023). "In order to exclude the possibility that the observed effect of NEK4 was cell‐ and cancer‐type specific, we employed two more breast cancer cell lines, MDA‐MB‐231 and MCF7, to validate molecular effect of NEK4." (PMID 30247800, 2018). "The mRNA level analysis of NEK genes in breast cancer cell lines and breast cancer patients from various data sources revealed that NEK2, NEK4, NEK5, NEK6, NEK8, and NEK11 are overexpressed in breast cancer and may be involved in breast cancer development." (PMID 37627077, 2023).
colorectal cancer (4 papers, 2016 to 2025). A primary or metastatic malignant neoplasm that affects the colon or rectum. "A decrease in NEK4 expression correlates with advanced stages of colorectal cancer, suggesting that NEK4 differentially regulates tumor progression and metastasis in various cancer subtypes." (PMID 41001016, 2025). "Inhibition of NEK4 further potentiated TRAIL-induced cell death in colorectal cancer cells such as DLD1 and RKO cells, and HeLa cervical cancer cells." (PMID 27602754, 2016). "We previously identified NEK4 as a target in squamous cell carcinoma, and others have found that it may impact colorectal cancer progression, whereas high expression of NEK4 promotes patient survival in clear cell renal cell carcinoma." (PMID 41001016, 2025). "First, NEK4 was identified to be differentially expressed across the four stages of colorectal cancer (CRC), showing that the higher the stage of CRC is the lower the level of NEK4 expression is." (PMID 32294979, 2020).
bipolar disorder (3 papers, 2021 to 2025). A disorder of the brain that causes unusual shifts in mood, energy, activity levels and the ability to carry out day-to-day tasks. "Findings: High expression of NEK4 was associated with a high risk of bipolar disorder (β-brain = 0.126, β-blood = 1.158) and major depression (β-brain = 0.0316, β-blood = 0.254)." (PMID 39950180, 2025). "Our study identified NEK4 as a key gene linked to both bipolar disorder (BD) and major depressive disorder (MDD), suggesting its potential as a drug target and a biomarker for differentiating BD subtypes." (PMID 39950180, 2025). "NEK4 has been suggested as a potential drug target in neurological disorders, including bipolar disorder and migraines, and control of circadian rhythms." (PMID 41001016, 2025). "Meaning: This implies that NEK4 as a potential drug target may contribute to the treatment of bipolar disorder and major depression." (PMID 39950180, 2025).
ciliopathy (2 papers, 2016 to 2020). A genetic disorder of the cellular cilia or the cilia anchoring structures, the basal bodies, or of ciliary function. "A genomic approach in patients with ciliopathy phenotypes led to the identification of seven novel candidates genes linked to ciliopathies, including loss-of-function mutations in NEK4." (PMID 32294979, 2020). "This interaction profile might be involved in ciliopathies, and NEK4 down-regulation may influence the susceptibility to those disorders." (PMID 32294979, 2020). "Similarly, NEK4 interacts with the known ciliopathy protein RPGRIP1L (mutations in RPGRIP1L are causative for Joubert and Meckel-Gruber syndromes), is localized to the basal body in ciliated cells, and its deficiency impairs cilium assembly." (PMID 27894351, 2016). "Of the remaining 40 families, nine (22.5%) had variants in eight novel candidate ciliopathy genes (TXNDC15, TRAPPC3, EXOC3L2, FAM98C, C17orf61, LRRCC1, NEK4, and CELSR2)." (PMID 27894351, 2016).
lung adenocarcinoma (2 papers, 2025). A carcinoma that arises from the lung and is characterized by the presence of malignant glandular epithelial cells. "NEK4 upregulation is associated with cell proliferation and metastasis in lung adenocarcinoma." (PMID 41001016, 2025). "In lung adenocarcinoma cells, NEK4 acts as a promoter of EMT by regulating the activity of suppressor of mothers against decapentaplegic 3 (SMAD3) and zinc finger E-box binding homeobox 1 (ZEB1) during transcriptional growth factor beta (TGF-β)-induced EMT." (PMID 41154634, 2025). "Additionally, Ding and colleagues reported that knockdown of NEK4 increased the expression of E-cadherin and inhibited the tumor formation in murine models of lung adenocarcinoma." (PMID 41154634, 2025). "Indeed, reducing NEK4 levels in mouse and human lung adenocarcinoma cells appeared to create resistance to Taxol but heightened the sensitivity of the cells to vincristine, which binds tubulin and disrupts microtubule polymerization." (PMID 41154634, 2025).
malaria (2 papers, 2012 to 2023). Malaria is a serious and sometimes fatal disease caused by a parasite that commonly infects a certain type of mosquito which feeds on humans. "The function of the nek-4 gene has been previously investigated in the rodent malaria parasite Plasmodium berghei; it was shown that disruption of Pbnek-4 does not affect asexual replication, gametocytogenesis and gametogenesis, but impairs differentiation of zygotes into ookinetes." (PMID 22849771, 2012).
diabetes (1 paper, 2017). "The obesity SNP rs2710323, together with two diabetes SNPs, rs2590838 (r2, 0.78) and rs1108842 (r2, 0.8), are located in loci that regulate genes (TMEM110, MUSTN1, ITIH4, NEK4, GNL3, PBRM1, and NT5DC2) within a 300 kb genomic region on chromosome 3." (PMID 29081791, 2017).
head and neck squamous cell carcinoma (1 paper, 2025). A squamous cell carcinoma that arises from any of the following anatomic sites: lip and oral cavity, nasal cavity, paranasal sinuses, pharynx, larynx, and salivary glands. "NEK4 enhances cell death and decreases cell viability and invasiveness in different cancer types, including lung, colon, and head and neck squamous cell carcinomas." (PMID 41001016, 2025).
squamous cell carcinoma (1 paper, 2025). A carcinoma arising from squamous epithelial cells.
sterility (1 paper, 2019). "Cross-fertilization studies, with pre-characterized sex-specific mutants, such as the male-deficient map2 or female-defective nek4 mutant, make it possible to identify gender-specific sterility phenotypes in P. berghei." (PMID 31797966, 2019).
triple-negative breast carcinoma (1 paper, 2025). An invasive breast carcinoma which is negative for expression of estrogen receptor (ER), progesterone receptor (PR), and human epidermal growth factor receptor 2 (HER2). "Understanding its role in cell cycle regulation could be valuable in developing therapeutic strategies and patient stratification, as we and others have identified NEK4 as a potential target for new drug development in triple-negative breast cancer." (PMID 41001016, 2025). "Never In Mitosis Gene A (NIMA)-related kinase 4 (NEK4), a serine/threonine protein kinase, is involved in several cellular processes, including the DNA damage response and mRNA splicing, and we identified it as a potential new drug target in triple-negative breast cancer." (PMID 41001016, 2025).